NDUFV2 (NADH:ubiquinone oxidoreductase core subunit V2)
Diseases named in the same sentence as NDUFV2 in open-access papers (continued):
Sharing a sentence is not in itself a finding about the gene and the disease.
autism (1 paper, 2023). Persistent deficits in social interaction and communication and interaction as well as a markedly restricted repertoire of activity and interest as well as repetitive patterns of behavior. "Since L1-70’s interactions with TOP1, PPARγ and NDUFV2 contribute to the expression of two essential long autism genes and regulate important neuronal functions, we propose that L1 may not only ameliorate neurological problems, but also psychiatric dysfunctions." (PMID 36768419, 2023).
breast carcinoma (1 paper, 2025). "However, NDUFV2, NDUFS2, and NDUFS3, whose expression levels have little impact on patient survival of any subtype of breast cancer, contain no Fe–S clusters or play no role in the main path of electron transport." (PMID 39873399, 2025).
hearing loss (1 paper, 2021). "We observed that several SNPs in SCARNA16, IQGAP2, PTPRK, GLI3, ADARB2 and NDUFV2, which have been reported to be significantly associated with several other types of hearing loss, were also significantly associated with NIHL in this study (all P values ≤ 0.05)." (PMID 33242228, 2021).
ischemia reperfusion injury (1 paper, 2023). Adverse functional, metabolic, or structural changes in ischemic tissues resulting from the restoration of blood flow to the tissue (reperfusion), including swelling; hemorrhage; necrosis; and damage from free radicals. "A recent study suggested that heart-specific knockout of Ndufs4 ameliorates ischemia-reperfusion injury, and another research even showed that low abundance of NDUFV2 and NDUFS4 subunits predicts mammalian longevity." (PMID 36741296, 2023).
lumbar disc degeneration (1 paper, 2022). "In summary, we conclude that the SNP rs145497186 related to NDUFV2 could be associated with susceptibility to lumbar disc degeneration and the degree of chronic low back pain in Asian people." (PMID 36309697, 2022).
melanoma (1 paper, 2024). A malignant, usually aggressive tumor composed of atypical, neoplastic melanocytes. "LONP1 over-expression results in impaired complex I assembly in melanoma cells, upregulation of NDUFB6,8,10 and 11, and downregulation of NDUFV1, NDUFV2, NDUFS3 and NDUFS7." (PMID 38263327, 2024).
neuroblastoma (1 paper, 2007). Neuroblastoma (NB) is the most common solid, extracranial childhood tumor. "Sp1 role in the regulation of complex I subunits, was demonstrated by the ability of the Sp1/DNA binding inhibitor, mithramycin, to inhibit the transcription of NDUFV1 and NDUFV2, in neuroblastoma cells." (PMID 17786189, 2007).
Stroke (1 paper, 2021). Sudden impairment of blood flow to a part of the brain due to occlusion or rupture of an artery to the brain. "The significant increase of NRF1 expression level was 20% (p < 0.01), that of TFAM was 50% (p < 0.01), that of NDUFV2 was 20% (p < 0.01), that of SDHA was 50% (p < 0.01), and that of VEGF was 40% (p < 0.01), compared to the Stroke + Saline group." (PMID 33806692, 2021). "In our stroke model, we observed a pronounced short-term PGC-1α activation, evidenced by a significant upregulation of PGC-1α-dependent proteins: NRF1, TFAM, catalytic subunits of the substrate-binding sites of the respiratory chain (NDUFV2 and SDHA), VEGF, and SYP." (PMID 33806692, 2021).
thyroid cancer (1 paper, 2025). "Notably, genes such as B4GALT1, ALDH1A1, NDUFV2, and ACO1 had mutations in 6% of samples, making them frequent mutational targets in thyroid cancer." (PMID 40861812, 2025).
uveal melanoma (1 paper, 2022). A melanoma derived from melanocytes of the uveal tract. "For example, NDUFV2, known as NADH ubiquinone oxidoreductase core subunit V2, might act as a prognostic factor in uveal melanoma." (PMID 35535359, 2022).
tumor (8 papers, 2019 to 2025). "This study is the pioneer to investigate that the NDUFV2 gene has been associated with the activity of inhibiting tumor cell proliferation, suggesting that the NDUFV2 gene may become a potential target for the study of tumor genesis and the development of antineoplastic drugs." (PMID 35471675, 2022). "The plasmids that were screened out with the best NDUFV2 gene silencing activity were then used to determine their inhibitory effects on the proliferation of the two drug-resistant tumor cells by MTT colorimetric assay." (PMID 35471675, 2022). "In response to the downregulation of NDUFV2 gene expression, massive and widespread effects on surviving cells and non-cancer cells, and also immune responses in the host that attenuate anti-tumor responses should be further explored." (PMID 35471675, 2022). "The mRNA expression of the NDUFV2 gene was detected by qRT-PCR, and the protein expression of NDUFV2 was detected by Western blot in each group of tumor cells after transfection." (PMID 35471675, 2022). "This research also revealed that anti-cancer agents—the AAs, which possess downregulating effect on both mentioned cell lines in this article, may inhibit the proliferation of drug-resistant tumor cells by downregulating NDUFV2 gene expression." (PMID 35471675, 2022). "In summary, the aim of this study was to construct a relationship between NDUFV2 gene downregulation and drug-resistant tumor cell proliferation, thereby demonstrating that AAs can inhibit the proliferation of drug-resistant tumor cells by downregulating NDUFV2 gene expression." (PMID 35471675, 2022). "In fact, of all protein subunits with significant differences in abundance between tumor and nontumor, only 4 were significantly upregulated in DEN-T: Ndufa13, Ndufs3, Ndufs8, and Ndufv2." (PMID 35756609, 2022). "It has been shown that the expression of the NDUFV2 gene in MCF-7/ADR and SMMC-7721/ADR cells is differentially downregulated by AAs, but the role of this gene expression in the growth of drug-resistant tumor cells has not been reported." (PMID 35471675, 2022).
cancer (4 papers, 2009 to 2025). A tumor composed of atypical neoplastic, often pleomorphic cells that invade other tissues. "Our previous research discovered that like these two plasmids, AAs can also decrease the expression of the NDUFV2 gene in both cancer cell lines." (PMID 35471675, 2022). "Among the core genes, NDUFA10 showed a low expression value in cancer patients across different expression profiles, while NDUFV2 showed a high expression value in cancer patients." (PMID 34124242, 2021). "NDUFV2 gene silencing could inhibit the proliferation of drug-resistant cancer cell lines, thus indicating a potential target for cancer treatment." (PMID 35471675, 2022). "This is also the first time to reveal that the NDUFV2-related pathways of mitochondrial complex I could have a relationship with the proliferation of tricky drug-resistant cancer cells." (PMID 35471675, 2022). "Among these, NDUFV2 and its closely related family member NDUFS3 highlight the potential involvement of mitochondrial dysfunction in cancer pathophysiology." (PMID 40861812, 2025). "Therefore, shRNA 3 and shRNA 2 were then selected for MTT assay to validate the cell viability of drug-resistant cancer cells MCF-7/ADR and SMMC-7721/ADR after downregulating the expression of their intrinsic NDUFV2 gene and protein." (PMID 35471675, 2022).
NDUFV2 also shares sentences with these, for which no sentence is quoted: Alzheimer disease (4 papers); Leigh syndrome (4); Huntington disease (2); major depression (2); ovarian carcinoma (2); Arrhythmia (1); Autoimmunity (1); brain diseases (1); disc degeneration (1); Down syndrome (1); ethylmalonic encephalopathy (1); ischemia (1); lung adenocarcinoma (1); lung carcinoma (1); neurological diseases (1); optic atrophy (1); paranoid personality disorder (1); Poretti-Boltshauser syndrome (1); psychiatric disorder (1); Sengers syndrome (1); Spastic paraplegia (1); thyroid disease (1).